CASP8 (caspase 8)
Diseases named in the same sentence as CASP8 in open-access papers (continued):
Sharing a sentence is not in itself a finding about the gene and the disease.
ileitis (12 papers, 2016 to 2025). "Upstream, loss of ZBP1 is sufficient to prevent ileitis in both mice with caspase-8- and FADD-deficient IECs." (PMID 35563804, 2022). "Similarly, MLKL deficiency inhibited ileitis caused by the removal of epithelial caspase-8 but only marginally mitigated ileitis in mice deficient in FADD in IECs, implying that MLKL promotes necroptosis or that its deficiency prevents necroptosis." (PMID 39118979, 2024). "The activated caspase-8 also processed gasdermin-D-mediated pyroptosis-like death of epithelial cells and ensuing ileitis." (PMID 39840043, 2024). "Supporting the need to regulate TNF-induced death in the intestines, IECs express Caspase-8 to protect them from TNF-induced death and to regulate their turnover rate, as exemplified by the development of ileitis in IEC-specific Caspase-8 deficient mice." (PMID 31699962, 2019). "Genetic ablation of either Caspase-8 or Fadd in intestinal epithelial cells (IECs) results in necroptosis and caspase-8-gasdermin-D-mediated pyroptosis-like death, leading to spontaneous ileitis and/or colitis." (PMID 39939579, 2025). "A number of genetic studies reveal that mice with genetic ablation of Caspase-8, Fas associated via death domain (Fadd), or SET domain bifurcated histone lysine methyltransferase 1 (Setdb1) in IECs develop spontaneous ileitis and colitis owing to sensitizing cells to RIPK3-mediated necroptosis." (PMID 36795486, 2023). "Furthermore, STAT1 alters the gene expression of Caspase-8 and Mlkl in the small intestine and interferon-induced cell death seems to plays a crucial role during Crohn's disease like ileitis." (PMID 34141714, 2021). "However, the co-ablation of caspase-8 and MLKL downstream of RIPK3 or FADD and RIPK3 in IEC fully protected against cell death and prevented ileitis in mice." (PMID 39840043, 2024).
lung adenocarcinoma (12 papers, 2013 to 2025). A carcinoma that arises from the lung and is characterized by the presence of malignant glandular epithelial cells. "Association of phosphotyrosine 380 Caspase-8 (p-Casp8) expression with clinicopathological characteristics of patients with operable lung adenocarcinoma (n = 84)." (PMID 34367939, 2021). "We retrospectively examined the association between p-Casp8 and p-Src in the patients with resectable lung adenocarcinoma." (PMID 34367939, 2021). "Accordingly, caspase-8 was strongly associated with c-Src overactivation in lung adenocarcinoma." (PMID 34367939, 2021). "Next, we compared caspase 8 expression in bulk-RNA-sequencing data from SCLC with lung adenocarcinoma (LUAD)." (PMID 41413044, 2025). "ANGPTL4 inhibited pyroptosis and apoptosis by regulating the NLRP3/ASC/Caspase 8 pathway, leading to resistance to gefitinib in lung adenocarcinoma." (PMID 36467503, 2022). "In our study, caspase-8 phosphorylated by c-Src predominantly enhanced c-Src activation to facilitate metastasis through attaining EMT phenotypic features in lung adenocarcinoma." (PMID 34367939, 2021). "Collectively, caspase-8 phosphorylated at tyrosine 380 by c-Src predominantly enhanced c-Src activation to induce EMT phenotypic features in lung adenocarcinoma." (PMID 34367939, 2021). "A question was then raised as to how caspase-8 most potently overactivated c-Src in lung adenocarcinoma." (PMID 34367939, 2021). "Our examination revealed that p-Casp8 was positively correlated with p-Src in the lung adenocarcinoma tissues." (PMID 34367939, 2021). "Consistently, we found that p-Casp8 reversely activated c-Src (pY416 c-Src or p-Src) via docking of phosphotyrosine 380 to the SH2 domain to restrain chemotherapy efficacy in lung adenocarcinoma." (PMID 34367939, 2021). "The expressions of caspase-8 and c-Src were examined using immunoblotting in the lung adenocarcinoma-derived cell lines, including A549, H522, PC9, H1975, H1650, H3255, and H23." (PMID 34367939, 2021). "Collectively, tyrosine 380 of caspase-8 in the c-Src-caspase-8 interaction was pivotal for metastasis through EMT in lung adenocarcinoma." (PMID 34367939, 2021). "We initially probed the interactive effects of caspase-8 and c-Src on the aggressive properties of lung adenocarcinoma." (PMID 34367939, 2021). "To further confirm the role of caspase-8 on c-Src overactivation in lung adenocarcinoma, we profiled a set of the potential activator of c-Src through the siRNA library." (PMID 34367939, 2021). "Our team found that c-Src phosphorylated caspase-8 at tyrosine 380 hampered the apoptosis of caspase-8 responding to chemotherapy in lung adenocarcinoma." (PMID 34367939, 2021). "We previously reported that necroptosis was predominant for chemotherapy-induced cell death in lung adenocarcinoma cells, owing to c-Src-induced caspase-8 phosphorylation to block apoptosis." (PMID 34367939, 2021). "This indicated that the extracellular stimuli maintained the basic activity of c-Src that initiated c-Src–caspase-8 interaction, while caspase-8 virtually overactivated c-Src in lung adenocarcinoma." (PMID 34367939, 2021). "It was of note that Y380A mutation in the holoprotein of caspase-8 attenuated the spontaneous metastasis and impaired EMT process in lung adenocarcinoma." (PMID 34367939, 2021). "In the present study, we have observed that BEL can induce S/G2 phase arrest and activate caspase-8/3 in vitro, thus significantly inhibiting the proliferation and cell migration of human A549 lung adenocarcinoma cells." (PMID 33299414, 2020). "Depletion of c-FLIP has differential effects on lung adenocarcinoma cell lines, but caspase-8 is necessary for lines to be sensitive to c-FLIP depletion." (PMID 26485762, 2015). "In lung adenocarcinoma cells MMP-2 siRNA induces Fas-mediated activation of caspase-8 and -9 and cleavage of Bid by increasing Fas and FasL in both in the cell membrane and in the medium." (PMID 23470450, 2013).
lung adenocarcinoma (continued). "Comparable data were obtained in the study of the antitumor activity of endogenous vesicles isolated from MSCs-TRAIL against resistant lung adenocarcinoma cells, where the significant apoptosis of the tumor cells was accompanied by caspase 8 activation after the addition of exosomes with TRAIL." (PMID 36661524, 2023). "Initially, caspase-8 phosphorylated at tyrosine 380 by c-Src predominantly enhancing c-Src activation to facilitate metastasis through attaining epithelial-mesenchymal transition (EMT) phenotype in lung adenocarcinoma." (PMID 34367939, 2021). "Therefore, we further dissected the interaction between c-Src and caspase-8 in lung adenocarcinoma cell lines." (PMID 34367939, 2021). "p-Src and p-Casp8 were ubiquitous in EGFR-mutant lung adenocarcinomas." (PMID 34367939, 2021). "Together, caspase-8 was able to exclusively overactivate c-Src in lung adenocarcinoma." (PMID 34367939, 2021). "It was observed that c-Src and caspase-8 was pivotal for EMT in lung adenocarcinoma." (PMID 34367939, 2021). "Collectively, ANGPTL4 inhibits lung adenocarcinoma cell pyroptosis and apoptosis by regulating the NLRP3\ASC\Caspase 8 pathway both in vivo and in vitro." (PMID 36467503, 2022). "c-Src overactivation by caspase-8 triggered EMT to facilitate tumor metastasis and yielded resistance to therapies in lung adenocarcinoma." (PMID 34367939, 2021). "Following phosphotyrosine 380 of caspase-8–mediated c-Src overactivation, we detected the downregulation of E-cadherin and upregulation of vimentin with morphological characteristics of spindle and dendritic shapes that could promote tumor metastasis in lung adenocarcinoma." (PMID 34367939, 2021). "Caspase-8 had the phosphotyrosine 380 docking to the SH2 domain of c-Src and “PDEP” motif binding to the SH3 domain of c-Src to overactivate c-Src in lung adenocarcinoma." (PMID 34367939, 2021). "The phosphorylation or lack of caspase 8 was essential for Paclitaxel-triggered necroptosis in lung adenocarcinoma cells." (PMID 35768485, 2022). "Surprisingly, c-Src inactivation through caspase-8 knockdown or dasatinib was able to block the survival-signaling-related tyrosine phosphorylation of EGFR, which, in turn, increased the antitumor activity of TKIs in EGFR-mutant lung adenocarcinoma." (PMID 34367939, 2021). "Therefore, it is of interest to explore the interaction between caspase-8 and c-Src and their effect on the clinical efficacy of TKIs in EGFR-mutant lung adenocarcinoma." (PMID 34367939, 2021). "Although activated c-Src did not enhance EGFR-related survival pathways in lung adenocarcinoma, the possibility of c-Src inactivation resulting in caspase-8 dephosphorylation to facilitate cell death was considered." (PMID 34367939, 2021). "This was substantiated by our observation that caspase-8 was rarely lacking in lung adenocarcinoma." (PMID 34367939, 2021). "Our team has done great work in exploring why caspase-8 dephosphorylation could not initiate apoptosis during dasatinib treatment in lung adenocarcinoma (data unpublished)." (PMID 34367939, 2021).
breast tumors (11 papers, 2003 to 2025). "Of the 35 upregulated genes, 5 were all related to breast tumor types: CASP8 (0.7-fold upregulation), CDH1 (1.21-fold upregulation), GATA3 (3-fold upregulation), ESR1 (3-fold upregulation) and FOXA1 (+ 2.89-fold upregulation)." (PMID 31182966, 2019). "However, only the ECs of cGAMP-treated implanted breast tumours exhibited high expression of pro-apoptotic genes, including CASP3, CASP8, APF1, BID, BAX, and BAK." (PMID 34285232, 2021). "However, SK-BR-3 breast tumour cells exhibiting increased expression level of Bcl-XL were resistant to TRAIL, though upon exposure to TRAIL, caspase-8 and Bid were activated." (PMID 12644829, 2003). "Our observation followed by statistical analysis of methylation status in breast tumors along with transcript expression revealed a negative correlation for TRAIL, DR4, CASP8, ATM, CHEK2, BRCA1 and BRCA2 CpG sites." (PMID 21092294, 2010). "However, there were no detectable differences in the expression levels of caspase-8 and FADD between SK-BR-3 and MDA-MB-231 breast tumour cells showing different sensitivities to TRAIL." (PMID 12644829, 2003).
Hyperglycemia (11 papers, 2018 to 2024). An increased concentration of glucose in the blood. "Activation of cPKCβII by hyperglycemia upregulates caspase 8-induced apoptosis in blood-brain barrier endothelial cells." (PMID 29744369, 2018). "Western blot analysis was performed to evaluate the induction of apoptosis by hyperglycemia, including the death receptor and mitochondrial pathways characterized by the expression of caspase-8 and caspase-9, respectively, which were evaluated as well as the downstream executor caspase-3." (PMID 33584279, 2020). "Increased levels of caspase-8 and ROS have both been detected in hyperglycemia-induced NTDs, and antioxidants could ameliorate NTD occurrence with decreased caspase-8 cleavage." (PMID 31064411, 2019). "In obese vs lean participants, Oncostatin-M, Caspase-8 and 4E-BP1 were more markedly suppressed during hypoglycemia, whereas VEGF-A was more markedly suppressed during hyperglycemia." (PMID 37400734, 2023). "Our results confirmed the effect of hyperglycemia in different tissues, indicating upregulation of apoptotic markers (BCL and caspase 8)." (PMID 36869348, 2023). "Uncontrolled hyperglycemia can then exacerbate β-cell ER stress, under which condition THADA aggravates ER stress-induced apoptosis through the pro-apoptotic complex of DR5/FADD/caspase-8." (PMID 36823211, 2023).
acute myeloid leukemia (10 papers, 2015 to 2025). Acute myeloid leukemia (AML) is a group of neoplasms arising from precursor cells committed to the myeloid cell-line differentiation. "In cancers, including acute myeloid leukemia, the apoptotic pathway is frequently inhibited by upregulating antiapoptotic proteins or downregulating caspase-8 and FADD." (PMID 34663800, 2021). "Birinapant, a bivalent Smac mimetic with high affinity for IAPs, acts through degradation of cIAP1 and caspase-8 activation in acute myeloid leukemia." (PMID 27223062, 2016). "HDAC inhibition by valproic acid has been demonstrated to upregulate TRAIL and its receptor DR5 in acute myeloid leukemia cells and thereby induces caspase-8 activation." (PMID 27738323, 2016). "The lead compound FLIPinB increased DL-induced caspase-8 activity as well as promoted cell death in HeLa, Jurkat and Acute Myeloid Leukemia (AML) cell lines." (PMID 39753884, 2025). "Similarly, in acute myeloid leukemia (AML), the forced expression of PPARγ regulated the induction of apoptosis via caspase-8 activation." (PMID 35954274, 2022). "In acute myeloid leukemia (AML) cells, NOB induces cell cycle arrest at the G0/G1 phase through downregulating ERK signaling pathway, increases cell apoptosis through activation of caspase-3, caspase-9, and caspase-8, and upregulates of MAPK signaling pathway in HL-60 cell line." (PMID 27761146, 2016).
Arthritis (10 papers, 2015 to 2026). Inflammation of a joint. "Intriguingly, a further study showed that conditional deletion of caspase-8 in dendritic cells (Caspase-8CD11c.cre/+) exacerbated arthritis, whilst, conversely, myeloid cell-specific caspase-8 loss (Caspase-8LysM.cre/cre) enhanced disease resolution." (PMID 33924766, 2021). "Caspase-8 is also implicated in the maintenance of synovial tissue-resident macrophages that can limit arthritis." (PMID 28978351, 2017). "Global loss of RIPK3 in both caspase-8 deletion constructs causes the response to arthritis to revert back to control levels via a mechanism potentially independent of cell death." (PMID 28978351, 2017). "Further, in CreCD11cCasp8flox/flox mice, caspase-8 is implicated in the maintenance of synovial tissue-resident macrophages that can limit arthritis development." (PMID 28978351, 2017). "Loss of function mutations preventing kinase activity of RIPK1 itself as well as heterozygous Casp8 cleavage-site mutations allowing unregulated activity of RIPK1 cause severe primary immunodeficiency, intestinal inflammation, arthritis, and CRIA in humans." (PMID 37965338, 2023). "In stark contrast to CreLysMCasp8flox/flox mice, CreCD11cCasp8flox/flox mice exhibited a more rapid and severe onset of arthritis, indicating that in this caspase-8-deletion construct, caspase-8 controls the magnitude of the initial inflammatory response." (PMID 28978351, 2017). "We showed that CreLysMCasp8flox/flox mice resolve K/BxN serum-transfer-induced arthritis more rapidly than control mice, which suggests that caspase-8 in this context prolongs the inflammatory response." (PMID 28978351, 2017). "Here, we investigated how caspase-8 signaling impacts development and progression of the acute K/BxN serum-transfer-induced arthritis model of inflammatory arthritis that resembles the effector stage of RA." (PMID 28978351, 2017). "We believe that future studies will elucidate new cell autonomous mechanisms by which caspase-8 regulates arthritis pathogenesis." (PMID 28978351, 2017). "We show here that caspase-8 in lysozyme M-expressing cells promotes a prolonged inflammatory response, as CreCD11cCasp8flox/flox mice exhibit reduced severity and accelerated resolution of K/BxN serum-transfer-induced arthritis." (PMID 28978351, 2017). "We show that intact caspase-8 signaling maintains opposing roles in lysozyme-M- and CD11c-expressing cells in the joint; namely, caspase-8 is crucial in CD11c-expressing cells to delay arthritis induction, while caspase-8 in lysozyme M-expressing cells hinders arthritis resolution." (PMID 28978351, 2017). "Therefore, we examined the involvement of caspase-8 within these antigen-presenting cell populations in the pathogenesis of an arthritis model that resembles the RA effector phase." (PMID 28978351, 2017). "Importantly, our findings reveal that a TLR–TRIF–RIPK3–caspase-8 signalling pathway may promote K/B × N arthritis disease persistence by driving IL-1β production via transcriptional induction, and/or cleavage induced activation." (PMID 25693118, 2015). "We postulate that caspase-8 deletion in the neutrophils and monocytes of CreLysMCasp8flox/flox mice that enter the joint under inflammatory conditions may contribute to the differing responses to K/BxN serum-transfer-induced arthritis in CreLysMCasp8flox/flox and CreCD11cCasp8flox/flox mice." (PMID 28978351, 2017). "In contrast to both models of CD11c-specific deletion of cFLIP, caspase-8 deletion in CD11c-expressing populations does not result in the spontaneous development of arthritis or neutrophilia." (PMID 28978351, 2017). "Considering IAPs regulate RIPK3 activity, and suppress K/B × N arthritis severity, we sought to determine if a TLR–TRIF–RIPK3 axis could regulate K/B × N arthritis via caspase-8 or MLKL signalling." (PMID 25693118, 2015).
Arthritis (continued). "Since caspase-8 may mediate its suppressive effect during K/BxN serum-transfer-induced arthritis independent of preventing RIPK3-mediated necroptosis, we sought to determine alternate modalities by which this RIPK3-mediated suppression potentially occurs." (PMID 28978351, 2017). "Caspase-8 is an endogenous suppressor of RIPK signaling; therefore, we examined whether unchecked RIPK3 signaling may contribute to the aberrant responses to K/BxN serum-transfer-induced arthritis observed in our CreLysMCasp8flox/flox and CreCD11cCasp8flox/flox caspase-8-deficient mice." (PMID 28978351, 2017).